ESM1 (endothelial cell specific molecule 1)
Diseases named in the same sentence as ESM1 in open-access papers (continued):
Sharing a sentence is not in itself a finding about the gene and the disease.
glioma (11 papers, 2016 to 2025). A benign or malignant brain and spinal cord tumor that arises from glial cells (astrocytes, oligodendrocytes, ependymal cells). "In the TCGA database, ESM1 expression was found to correlate with higher glioma grade and shorter survival of GBM patients." (PMID 39773984, 2025). "A long noncoding RNA HULC (highly upregulated in liver cancer) was positively correlated with ESM1 in human gliomas." (PMID 36522312, 2022). "HULC silencing suppressed glioma cell proliferation and invasion, which were reversed after ESM1 overexpression." (PMID 36522312, 2022). "The expression of HULC and endothelial cell specific molecule 1 (ESM-1) in glioma tissue is positively correlated with microvessel density and hierarchical dependence." (PMID 35183058, 2022). "HULC silencing suppressed angiogenesis by regulating ESM-1 via the PI3K/Akt/mTOR signaling pathway in human gliomas." (PMID 32010942, 2020). "ESM1 could also exert a pro-angiogenesis effect via PI3K/Akt/mTOR signaling in human gliomas." (PMID 36522312, 2022). "Additionally, we found that HULC silencing could suppress the expression of ESM-1 in the glioma U87MG and U251 cell lines." (PMID 26894862, 2016). "We found that the levels of HULC, VEGF, ESM-1 (endothelial cell specific molecule 1) and microvessel density (MVD) (CD34) were correlated in glioma patient tissues of various grades." (PMID 26894862, 2016). "After calculating the correlations among the expression levels of HULC, VEGF, ESM-1 and MVD (CD34), we observed a significant linear correlation between HULC, VEGF, ESM-1 and MVD (CD34) in primary glioma patient pathological tissue." (PMID 26894862, 2016). "We studied the levels of HULC, ESM-1 and angiogenesis (CD34 and VEGF) in the tissues of glioma patients." (PMID 26894862, 2016). "Furthermore, there was a positive correlation between the level of HULC, ESM-1, MVD (CD34) and VEGF in glioma patient tissue, suggesting that there was a potential relationship between HULC, ESM-1 and angiogenesis in the tumor progression." (PMID 26894862, 2016).
atherosclerosis (10 papers, 2018 to 2024). A disease characterized by the build-up of fatty material and calcium deposition in the arterial wall resulting in partial or complete occlusion of the arterial lumen. "Hepatocyte growth factor has been associated with incident type 2 diabetes, and endothelial cell specific molecule 1, with atherosclerosis in subjects with diabetes." (PMID 30237882, 2018). "ESM-1 is a proteoglycan mainly secreted by activated endothelial cells, which is thought to be implicated in angiogenesis, vascular remodelling, inflammation and atherosclerosis." (PMID 38524235, 2024). "Another marker of endothelial dysfunction is endothelial cell-specific molecule-1 (ENDOCAN), which is associated with systemic inflammation, DM, atherosclerosis, hypertension, and acute coronary syndrome." (PMID 37371510, 2023). "Such evidence suggests that both ESM-1, which is related to endothelial function, and Gal-3, which is related to atherosclerosis, have the potential to serve as biomarkers for STEMI." (PMID 36388167, 2022). "In addition, KEGG analysis revealed that these 159 ESM1-specific binding proteins were mostly enriched in carbon metabolism, glycolysis/gluconeogenesis, lipids, and atherosclerosis." (PMID 38720298, 2024). "More mechanistic studies investigating the relationship between HIV, ART and ESM-1 ought to be carried as this could be provide a possible target that can be used to predict or modulate endothelial cell activation and subsequently atherosclerosis." (PMID 37161496, 2023).
bladder cancer (10 papers, 2021 to 2025). "For instance, in bladder cancer, a specialized endothelial cell subtype known as S1 ECs expresses the key marker gene ESM1." (PMID 41303611, 2025). "It has also been suggested that BMSC-derived exosomal miR-9-3p repressed bladder cancer progression through Endothelial cell-specific molecule 1 (ESM1) downregulation, presenting a novel therapeutic target for bladder cancer therapy." (PMID 36463254, 2022). "For example, BMMSC-EVs containing miR-206 inhibits osteosarcoma progression by targeting transformer 2β (TRA2B), and containing miR-9-3p inhibits the growth and metastasis of bladder cancer by targeting ESM1 (Endothelial cell specific molecule 1) gene expression." (PMID 35915054, 2022).
ovarian carcinoma (9 papers, 2023 to 2026). A malignant neoplasm originating from the surface ovarian epithelium. "ESM1 is overexpressed in non-small cell lung cancer, clear cell renal cell carcinoma and ovarian cancer, to regulate tumor progression." (PMID 36890467, 2023). "In ovarian cancer, HIF-1α upregulates endothelial cell-specific molecule 1 (ESM1), which enhances PKM2 SUMOylation and stabilizes its dimeric form." (PMID 40842995, 2025). "Because it was found that shikonin inhibits the molecular interaction between ESM1 and PKM2, thus preventing the formation of PKM2 dimers and inhibiting glycolysis and fatty acid synthesis in ovarian cancer." (PMID 40191206, 2025). "In the hypoxic microenvironment of ovarian cancer, HIF-1α upregulates endothelial cell-specific molecule 1 (ESM1), which induces PKM2 SUMOylation and stabilizes its dimeric conformation." (PMID 40842995, 2025). "Furthermore, our study revealed that Shikonin effectively inhibits the molecular interaction between ESM1 and PKM2, consequently preventing the formation of PKM2 dimers and thereby inhibiting ovarian cancer glycolysis, fatty acid synthesis and vasculogenic mimicry." (PMID 38720298, 2024).
diabetes (8 papers, 2017 to 2025). "Hypertension, diabetes and renal function is independently associated with circulating ESM-1 levels and ESM-1 levels are closely correlated with blood pressure, FBG, serum uric acid and creatinine levels." (PMID 31429753, 2019). "In DN-resistant, compared to DN-susceptible mice, urine Esm-1 was significantly increased with diabetes." (PMID 28934365, 2017). "The study aims to evaluate serum endocan (endothelial cell-specific molecule-1) levels in patients with type 2 diabetes mellitus and to determine its relationship with disease activity by comparing it with a control group." (PMID 41578817, 2025). "In summary, these findings suggest that ESM-1 may serve as an immunoinflammatory biomarker in diabetes and a warning for the development of potential complications." (PMID 41578817, 2025). "Conversely, serum Esm-1 was surprisingly decreased with diabetes." (PMID 28934365, 2017). "In contrast to urine levels, diabetes significantly decreased circulating Esm-1." (PMID 28934365, 2017). "Additionally, diabetes-associated genes such as RASGRP3, SIRPA, GATM and ESM1 were downregulated." (PMID 33923831, 2021). "The mechanism of decreased serum Esm-1 in diabetes is unknown." (PMID 28934365, 2017). "Therefore, to test whether Esm-1 protein expression in glomeruli is regulated by diabetes, we isolated and cultured glomeruli, and assayed for Esm-1 in conditioned media by ELISA." (PMID 28934365, 2017). "Of the downregulated genes, ESM1 and RASGRP3 are examples of genes differentially methylated in gestational diabetes, showing the growing emergence of links between diabetes and epigenetic regulation." (PMID 33923831, 2021). "Other studies have also reported that patients with type 2 DM had higher amounts of ESM-1 in the circulation than those without diabetes." (PMID 41578817, 2025). "Moreover, patients with diabetes had higher concentrations of GDF-15 (p = 0.017) and Troponin-T (p = 0.013), and lower concentrations of ESM-1 (p = 0.048)." (PMID 35859587, 2022).
Hypertension (8 papers, 2017 to 2025). The presence of chronic increased pressure in the systemic arterial system. "Our previous research showed that ESM1 levels increased in an L-NAME/high-salt-induced hypertension mouse model and influenced the expression of downstream adhesion molecules." (PMID 40332339, 2025). "ESM-1 has emerged as a potential biomarker in humans, as it is significantly correlated with cardiovascular diseases, including hypertension, coronary artery disease, and heart failure." (PMID 35790968, 2022). "Considering that ESM-1 is elevated in hypertensive dogs, hypertension is considered to affect eGCX, and its possible effects on cardiovascular disease in dogs remain to be elucidated." (PMID 35790968, 2022). "Clinical data indicate that ESM1 is positively correlated with hypertension." (PMID 37968862, 2024). "In the early stages of hypertension, the ESM1 concentration in plasma is significantly increased." (PMID 37968862, 2024). "Several studies have demonstrated a link between serum concentrations of ESM1 and hypertension and cardiovascular disease, as well as renal damage, suggesting it may have clinical utility as an inflammatory biomarker." (PMID 32889533, 2020).
non-small cell lung carcinoma (8 papers, 2016 to 2024). A group of at least three distinct histological types of lung cancer, including non-small cell squamous cell carcinoma, adenocarcinoma, and large cell carcinoma. "Besides, ESM1 mediated the progression of non-small cell lung cancer with EGFR mutation." (PMID 37476182, 2023). "ESM1 can also promote the development of non-small cell lung cancer by regulating the expression of HIF1α." (PMID 38201620, 2023). "Furthermore, another study reported that ESM-1 expression was regulated via the JAK/STAT3 pathway in EGFR-activated non-small-cell lung cancer cells and induced by FoxO1 nuclear localization in cultured endothelial cells under hypoxic conditions." (PMID 36077661, 2022).
lung carcinoma (7 papers, 2017 to 2024). "Studies have found that ESM-1 is highly expressed in many human solid tumors such as lung cancer, breast cancer, uterine cancer and kidney cancer." (PMID 38954708, 2024). "Progranulin (PGRN), endothelial cell-specific molecule-1, clusterin (CLU), and human epididymis protein 4 (HE-4) are novel proteins reported to have diagnostic and prognostic potential in lung cancer." (PMID 36595996, 2022). "Gu X figured out that ESM1/HIF−1α pathway appeared to be pivotal mediator of chronic intermittent hypoxia−induced lung cancer progression." (PMID 34858850, 2021). "ESM-1 has been reported to be over-expressed in lung cancer and significantly upregulated in malignant pleural effusion." (PMID 33489036, 2020). "In our previous study, we demonstrated ESM1's importance in activating the EGFR in lung cancer." (PMID 39309430, 2024). "ESM1 can guide the treatment of lung cancer to a certain extent." (PMID 38954708, 2024). "ESM-1 has been found highly over-expressed in some cancer tissues which could be a new biomarker for many cancers including lung cancer." (PMID 28514746, 2017). "In a previous study, we identified aas 1‒46 of ESM1 as crucial for the association with the extracellular domain of the EGFR and developed two peptide fragments of ESM1, including 1‒27 (peptide 1) and 26‒46 aas (peptide 2), to block the interaction of ESM1 and EGFR in lung cancer cells." (PMID 39309430, 2024). "While the level of ESM-1 was significantly higher among the patients with lung cancer than that of those in the transudate group, ESM-1 concentrations to help distinguish other exudative fluids (TB and parapneumonic) from MPE could not be obtained in our study." (PMID 36595996, 2022). "Our previous study showed that ESM1 could directly bind to the extracellular domain (ECD) of the EGFR and enhance EGF binding, thereby increasing EGFR phosphorylation and downstream signal transduction in lung cancer." (PMID 39309430, 2024).
esophageal cancer (6 papers, 2021 to 2023). A primary or metastatic malignant neoplasm involving the esophagus. "In esophageal cancer, ESM1 is an independent prognostic factor and facilitates the proliferation and migration of esophageal cancer cells through the Janus kinase (JAK) signaling pathway." (PMID 37476182, 2023). "The effect of silencing the ESM1 gene on the proliferation ability of esophageal cancer cells was assessed through a monoclonal proliferation assay." (PMID 35937390, 2022). "In this study, the effects of silencing ESM1 on the proliferation, migration, and invasion of esophageal cancer cells were observed by a monoclonal proliferation assay, wound healing assay, and Transwell assay, respectively." (PMID 35937390, 2022). "Compared with matched adjacent normal tissue, the mRNA expression level of ESM1 in esophageal carcinoma was significantly elevated." (PMID 35937390, 2022). "A recent study identified that overexpressed ESM1 exerted as a novel oncogene for esophageal cancer." (PMID 34858850, 2021). "ESM1 silencing inhibited the migration and invasion of esophageal cancer cells." (PMID 35937390, 2022). "The protein expression level, namely, endocan, was remarkably expressed in esophageal cancer tissues and weakly expressed in adjacent normal tissue by IF, and the mean fluorescent intensity of ESM1 in esophageal carcinoma was also elevated compared with matched adjacent normal tissue (p < 0.01)." (PMID 35937390, 2022). "However, the sophisticated and precise regulatory mechanism of ESM1 in esophageal cancer needs further study." (PMID 35937390, 2022). "Herein, this study intends to combine a bioinformatics approach and molecular biological experiments to verify ESM1 as the hub gene in esophageal cancer and thereby further identify the clinical and biological function as well as survival prognosis of ESM1 in ESCC." (PMID 35937390, 2022). "We subsequently explored the biological function of ESM1 in esophageal cancer cells." (PMID 35937390, 2022). "Esophageal cancer (ESCA) was accompanied by high upregulation of ESM1, which could be partly explained by cell proliferation and migration and the regulation of the Janus kinase (JAK) signaling pathway." (PMID 34007851, 2021). "ESM1 is a hub gene in the initiation and progression of ESCA/ESCC that promotes the proliferation, migration, and invasion of esophageal cancer cells and may be a promising therapeutic target and prognostic indicator." (PMID 35937390, 2022).
lymph node metastasis (6 papers, 2017 to 2024). "In the clinic, we found that ESM1 was upregulated in GC and was associated with advanced clinical stages, lymph node metastases, vascular invasion, and poor prognoses." (PMID 39309430, 2024). "In the present study, we showed that ESM1 is a poor prognostic factor, and its overexpression was associated with advanced clinical stage development, vascular invasion, and lymph node metastasis in GC patients." (PMID 39309430, 2024). "Moreover, elevated ESM1 expression was significantly associated with higher histology grade, deeper depth of infiltration, lymph node metastasis, and TNM stage (P < 0.05), suggesting that ESM1 may be a potential marker for clinical prognosis." (PMID 36117773, 2022). "In datasets GSE13861 and GSE66229, significantly higher levels of ESM1 transcripts were observed in GC patients with advanced clinical stages (stage 4) and lymph node metastasis (N3) compared to patients with earlier clinical and N stages." (PMID 39309430, 2024). "Compared with normal healthy controls, the more lymph node metastases there were, the higher the ESM1 expression, except at the N2 stage, which might be due to only 4 patients (p < 0.01)." (PMID 35937390, 2022). "The correlation between the ESM1 level and clinical data of OC patients was further confirmed, including FIGO stage, lymph node metastasis, and recurrence." (PMID 36594088, 2023). "Moreover, we found that ESM1 expression was significantly correlated with multiple clinical pathological parameters based on IHC staining, including the FIGO stage, lymph node metastasis, and recurrence." (PMID 36594088, 2023). "It was suggested that SNHG14, miR-211-3p and ESM1 in BCa were linked with TNM stage, tumor invasion stage and lymph node metastasis, but was not with gender, age, pathological grade or tumor size." (PMID 33482820, 2021).
triple-negative breast carcinoma (6 papers, 2019 to 2023). An invasive breast carcinoma which is negative for expression of estrogen receptor (ER), progesterone receptor (PR), and human epidermal growth factor receptor 2 (HER2). "In triple-negative breast cancer, high expression of ESM1 promotes tumor cell migration, proliferation and invasion through the Akt/NF-κB/Cyclin D1 signaling pathway." (PMID 37476182, 2023). "Here, we found that ESM1 was overexpressed in bevacizumab-resistant triple-negative breast cancer cells and was involved in increased tumor angiogenesis and metastasis." (PMID 36428773, 2022). "Deletion or neutralization of ESM1 significantly inhibited tumor growth and overcame bevacizumab resistance in triple negative breast cancer, thus confirming that ESM1 was a key molecule mediating bevacizumab resistance." (PMID 36428773, 2022). "In addition, compared to the patients with lesser expression of ESM1, those with highly expressed ESM1 were reported to have an obviously worse relapse-free survival in triple-negative breast cancer." (PMID 31354635, 2019).
clear cell renal cell carcinoma (5 papers, 2021 to 2024). "ESM1 was found to be clearly overexpressed in clear cell renal cell carcinoma, and is also one among the 59 stage-4 salient genes from our study." (PMID 39484215, 2024). "ESM-1 is greatly elevated in clear cell renal cell carcinoma." (PMID 33482820, 2021).
head and neck squamous cell carcinoma (5 papers, 2019 to 2023). A squamous cell carcinoma that arises from any of the following anatomic sites: lip and oral cavity, nasal cavity, paranasal sinuses, pharynx, larynx, and salivary glands. "In head and neck squamous cell carcinoma (HNSC), ESM1 was significantly overexpressed, and it may promote HNSC progression through the Ras-MAPK-ERK signaling pathway." (PMID 37476182, 2023).
kidney cancer (5 papers, 2008 to 2026). Primary or metastatic malignant neoplasm involving the kidney. "ESM1 (endothelial cell-specific molecule 1, alias endocan), crucially involved in cell growth regulation, vascular remodeling and angiogenesis, is dramatically over-expressed in endothelial cells of kidney cancers and other tumors, in association with increased tumor aggressiveness and vascularity." (PMID 18194544, 2008). "Consistent with previous research, we observed elevated levels of HAVCR1, MMP7, and ESM1 in kidney cancer patients." (PMID 40928391, 2026). "Studies using microarray and specific antibodies against ESM1 had revealed ESM1 to be a candidate biomarker in various cancers, including lung, breast, colon and kidney cancers." (PMID 28108731, 2017). "We also observed associations between 131 proteins and risk of liver cancer that included IGFBP7 and IGFBP3 [1.65 (1.48–1.84) and 0.46 (0.39–0.54), respectively], and 51 proteins and risk of kidney cancer, such as HAVCR1 and ESM1 [2.88 (2.55–3.24) and 1.84 (1.55–2.19)]." (PMID 38750076, 2024).
Obesity (5 papers, 2018 to 2024). Accumulation of substantial excess body fat. "Based upon own previous findings in adolescent offspring of GDM women, we investigated the link between maternal diabetes and obesity in pregnancy, and the epigenetic reprogramming of ESM1, MS4A3, and TSPAN14 genes, in adult offspring blood cells and subcutaneous adipose tissue." (PMID 35740266, 2022).